SCARNA21 (small Cajal body-specific RNA 21)
Synonyms: ACA68; SCARNA21A
Gene: Small Cajal body-specific RNA gene on chromosome 17 (7,906,122 to 7,906,260, forward strand). Ensembl gene ENSG00000252835.
Gene Ontology:
Biological process: RNA processing
Cellular component: Cajal body; nucleolus
Homologues: Orthologues: chimpanzee SCARNA21 (99% identical), guinea pig SCARNA21 (83% identical), mouse Gm22442 (82% identical).